RN7SL128P (RNA, 7SL, cytoplasmic 128, pseudogene)
Gene: Miscellaneous RNA gene on chromosome 6 (20,421,583 to 20,421,887, reverse strand). Ensembl gene ENSG00000240869.
Homologues: Orthologues: chimpanzee Metazoa_SRP (98% identical), macaque Metazoa_SRP (88% identical), guinea pig Metazoa_SRP (69% identical). Paralogues in human: RN7SL2 (79% identical), RN7SL1 (79% identical), RN7SL3 (77% identical), RN7SL5P (75% identical), RN7SL4P (75% identical), RN7SL769P (74% identical), RN7SL478P (74% identical), RN7SL230P (74% identical), RN7SL296P (73% identical), RN7SL408P (73% identical), RN7SL444P (73% identical), RN7SL743P (73% identical), and 699 more.